CCNB1 (cyclin B1)
Diseases named in the same sentence as CCNB1 in open-access papers (continued):
Sharing a sentence is not in itself a finding about the gene and the disease.
cervical cancer (36 papers, 2008 to 2025). A primary or metastatic malignant neoplasm involving the cervix. "In the present study, we found that SB induced cell cycle arrest at G2/M phase and reduced the protein expressions of cdc25C, CDK1, and cyclin B1 in cervical cancer cells, which may be the mechanism of action underlying the SB-inhibited cervical cancer cell proliferation." (PMID 32226384, 2020). "They further demonstrated that KLK5 inhibition in cervical cancer cells decreases radioresistance by downregulating G2/mitotic-specific cyclin-B1 (cyclin B1) expression and blocking the transition to the G2/M phase." (PMID 40072068, 2025). "Of late, Cyclin B1 that is primarily involved in cell-cycle regulation has been investigated for its over- expression in breast and cervix cancers." (PMID 36210467, 2022). "In a recent study, LncRNA CRNDE was found to acts as an oncogene in cervical cancer through sponging miR-183 to regulate CCNB1 expression." (PMID 34232111, 2021). "Nevertheless, we demonstrated that BCA-M treatment in all tested human cervical cancer cell lines commonly induced a down-regulation of cyclin B1 gene expression and induced cell cycle arrest at S and/or G2/M phases." (PMID 33050217, 2020). "The results showed that SB down-regulated the expressions of CDK1, cyclin B1, and cdc25C at protein levels, which further suggests that SB induces G2/M cell cycle arrest in cervical cancer cells." (PMID 32226384, 2020). "For example, lncRNA CRNDE sponges miR-183 to regulate cyclin B1 (CCNB1) expression in cervical cancer, and also promotes the epithelial-mesenchymal transition(EMT) in liver cancer cells by activating the Wnt/β-catenin signaling pathway." (PMID 33088214, 2020). "Downregulation of EPS8 using shRNAs suppressed expression of FOXM1 and the FOXM1-target CCNB1, and slowed down G2/M transition in cervical cancer cells." (PMID 30941306, 2019). "Expression of cyclin B1, phosphorylated cyclin B1 and p21 increased in cervical cancer following CKD-602 treatment." (PMID 31138113, 2019). "Cyclin B1 is very often found to be overexpressed in primary breast and cervical cancer cells as well as in cancer cell lines." (PMID 19113992, 2008). "In this communication we show that the knockdown of cyclin B1, the regulatory subunit of Cdk1, inhibited cell proliferation and induced apoptosis in various breast and cervical cancer cell lines." (PMID 19113992, 2008). "Taken together, the data strengthen the notion of cyclin B1 being required for the survival and proliferation of breast and cervical cancer cells and depletion/downregulation of cyclin B1 inhibits proliferation of cancer cells in vitro as well as in vivo." (PMID 19113992, 2008). "Downregulation of cyclin B1 inhibited proliferation of several breast and cervical cancer cell lines including MCF-7, BT-474, SK-BR-3, MDA-MB-231 and HeLa." (PMID 19113992, 2008). "This work demonstrates that cyclin B1 is required for survival and proliferation of breast and cervical cancer cells." (PMID 19113992, 2008). "We speculate that TCP11 gene may block the cell cycle by regulating the expression of CDK1/Cyclin B1, thereby inhibiting the proliferation of cervical cancer cells." (PMID 37697257, 2023). "Our previous study demonstrated that artemisinin might be a potential radiosensitizer through regulating the expression of G2 checkpoint-related proteins such as Wee 1 and cyclin B1 in human cervical cancer cells." (PMID 33194761, 2020).
cervical cancer (continued). "The role that SFN may plays in the inhibition of tumor growth was highlighted by the delay of mitosis through the down-regulation of cyclin B1 and the dissociation of the cyclin B1/CDC2 complex by GADD45β in cervical cancer cell lines." (PMID 27626412, 2016). "Moreover, cyclin B1 mRNA is significantly stabilized in cervical cancer cells infected with human papillomavirus type 18 (HPV 18) through upregulating HuR, a ubiquitously expressed member of the Hu family of RNA-binding proteins." (PMID 19113992, 2008). "They suggested that sulforaphane might delay the development of cervical cancer cells by arresting cell growth in the G2/M phase via the down-regulation of the cyclin B1 gene expression, dissociation of the cyclin B1/CDC2 complex, and the up-regulation of GADD45β proteins." (PMID 31284691, 2019). "Thus, targeting cyclin B1, leading consequently to the inactivation of Cdk1, could be a promising specific strategy for cell cycle intervention against breast and cervical cancer." (PMID 19113992, 2008). "Our results showed that Drp1-knockdown in cervical cancer cells reduced the G2/M cell cycle arrest and reversed the reduction of CDK1, cyclin B1 and cdc25C expressions compared to control cells upon SB treatment." (PMID 32226384, 2020). "YM Cheng found that sulforaphane may dissociate the cyclin B1/CDK1 complex by up-regulating GADD45B protein, thereby arresting in the G2/M phase and inhibiting the proliferation of cervical cancer." (PMID 40855561, 2025). "After combination of the expression pattern and survival analysis, eight upregulated hub gens (CCNB1, BUB1, CDK1, AURKB, KIF11, PBK and NUSAP1) stood out with dramatical upregulation in cervical cancer and were significantly correlated with good prognosis of cervical cancer (P < 0.05)." (PMID 33682613, 2021). "Then, the top 40 hub genes were conducted to evaluate the expression and prognostic values of cervical cancer and 7 upregulated (BUB1, CCNB1, CDK1, AURKB, KIF11, PBK, NUSAP1) and 1 downregulated (ESR1) hub genes were selected to have significant values as biomarkers." (PMID 33682613, 2021). "Further investigation demonstrated that over-expression of MEG3 promotes apoptotic cell death and induces G2/M cell cycle arrest in cervical cancer (HeLa) and retinoblastoma (C33A) derived cell lines through the decrease of CDK1 (cyclin-dependent Kinase 1) and CCNB1 (cyclin B1) levels." (PMID 29069869, 2017). "Cervical carcinoma HeLa cells express a high level of cyclin B1 (data not shown)." (PMID 19113992, 2008).
glioblastoma (33 papers, 2002 to 2026). The most malignant astrocytic tumor (WHO grade IV). "The CCNA1/CCNB1/CDK1/p21CIP1 pathway is associated with G2/ M-phase arrest in glioblastoma cells." (PMID 35246013, 2022). "Therefore, MSI1-KD probably leads the glioblastoma cells to undergo mitotic catastrophe, resulting in cell death caused by the accumulations of Numb and Cyclin B1 proteins and by the inhibition of Notch." (PMID 22428049, 2012). "In conclusion, we have reported that the molecular mechanism through which Mxi1 can act as an inhibitor of proliferation and tumorigenesis of U87 glioblastoma cells includes the inhibition of cyclin B1 promoter activity through the E-box and the possible consequent loss of cyclin B1 accumulation." (PMID 11875718, 2002). "For grade 4 glioblastoma brain cancer, CCNB1 was indicated as a part of hub genes (with CDC6, KIF23, and KIF20A) and its expression correlated with prognosis, suggesting it as a potential biomarker for diagnosis and as a target for treatment." (PMID 39409884, 2024). "Complete DYRK1A inhibition, as would be expected here with VER‐239353, resulted in cyclin B1 stabilization and accumulation in glioblastoma cells leading to CDK1 inhibition and cell cycle arrest." (PMID 34708541, 2021). "MXI1 acted as a tumor suppressor in human glioblastomas involving the transcriptional downregulation of cyclin B1 gene expression." (PMID 32695826, 2020). "Our results indicated that ENMD-2076 induced the G2-M phase cell cycle arrest of glioblastoma cells by down-regulating cyclin B1 phosphorylation." (PMID 31706255, 2019). "In glioblastoma, anti-miR-182 expression results in increased expression of biomarkers for proliferation and stem cell biomarkers (e.g., CCNB1, CD44, Sox2, and Nestin)." (PMID 31007608, 2019). "Using RNA-sequencing and western blotting analyses, we also found that AKBA arrested the cell cycle at the G2/M phase by regulating the p21/FOXM1/cyclin B1 pathway and inhibited mitosis of glioblastoma cells by downregulating the Aurora B/TOP2A pathway." (PMID 29970196, 2018). "Immunoblot analysis revealed that MSI1-KD in glioblastoma cells resulted in the accumulation of Cyclin B1 due to prolongation of the M-phase." (PMID 22428049, 2012). "Here we demonstrate that during the Mxi1-induced G2/M block in glioblastoma cells, the expression of the master regulatory gene of the G2 progression, cyclin B1 is down-regulated at transcriptional level, indicating that cyclin B1 is a target of Mxi1 activity." (PMID 11875718, 2002). "VPA treatment may promote apoptosis in glioblastoma cells by modulating critical proteins such as Bcl-xL, p21, Bim, and cyclin B1." (PMID 40794328, 2025). "Moreover, CCNB1, MAPK7, CD44, and CDC42 oncogenes have been associated with patients’ clinical outcomes in glioblastoma and it has been identified in simulation studies for druggable candidates of SJ10." (PMID 39409884, 2024). "Interestingly, the growth arrest of U-87 glioblastoma cells coincided with the formation of Max–Mxd2 heterodimers that bound to a consensus E-box in the proximal promoter of the CCNB1 (cyclin B1) gene and suppressed its transcription." (PMID 35203395, 2022). "Therefore, from the data above we found that TBMS1 blocks glioblastoma cells in G2/M phase by inhibiting the expression of Cyclin A2, Cyclin B1, and CDK1." (PMID 31349699, 2019). "The data are consistent with a mechanism in which AKBA arrested the cell cycle in glioblastoma cells at the G2/M phase by regulating the p21/FOXM1/cyclin B1 pathway, inhibited mitosis by downregulating the Aurora B/TOP2A pathway, and induced mitochondrial-dependent apoptosis." (PMID 29970196, 2018). "Furthermore, in GBM glioblastoma cells, CA promoted apoptosis by inducing cell cycle arrest and degradation of cyclin B1, RB, SOx2 and GFAP, molecules involved in cell survival and maturation processes." (PMID 27869665, 2016).
glioblastoma (continued). "However, in our glioblastoma cells, Cyclin B1 was probably appropriately down-regulated by MSI1 through an indirect or direct pathway." (PMID 22428049, 2012). "Though further studies are required to validate the suggested roles of MTR and CCNB1 in glioblastoma multiforme, our results demonstrate that CANGES is able to produce experimentally testable hypotheses that offer a solid ground for advanced analyses." (PMID 21533266, 2011). "Thus, our findings indicate that Mxi1 can act as a tumour suppressor in human glioblastomas through a molecular mechanism involving the transcriptional down-regulation of cyclin B1 gene expression." (PMID 11875718, 2002). "To identify FOXM1 transcriptional activity in hypoxic glioblastoma cells, we focused on and investigated the protein expression of PLK1 and cyclin B1, two well-known downstream targets of FOXM1." (PMID 34740322, 2021). "We here show that SFRP2-overexpression decreases CCNE1, CCND1 and CCNB1, and at the same time decreases SOX2 protein and overall cell proliferation in glioblastoma cells." (PMID 34021259, 2021). "Here, we also observed increased cyclin B1, A and D1 expression in U87MG glioblastoma cells following complete DYRK1A/B inhibition with VER‐239353." (PMID 34708541, 2021). "Top hub nodes from glioblastoma multiforme networks contain six matches, namely cyclin dependent kinase 2 (CDK2), cyclin A2 (CCNA2), cyclin B1 (CCNB1), erb-b2 receptor tyrosine kinase 2 (HER2), cyclin E1 (CCNE1), and cyclin D3 (CCND3)." (PMID 31952211, 2020). "In summary, our results demonstrated that BMAL1 as an anti-glioblastoma gene suppresses proliferation, migration, and invasion of U87MG cells by the downregulation of cyclin B1, p-AKT, and MMP-9." (PMID 32231148, 2020). "Treatment of glioblastoma cells with AKBA significantly decreased the ratio of p-CKD1/CDK1 and cyclin B1 suggesting that AKBA arrested the cell cycle at the G2/M phase, thereby inhibiting cell proliferation." (PMID 29970196, 2018). "Our findings suggest that AKBA can arrest cell cycling at the G2/M point by regulating the p21/FOXM1/cyclin B1 pathway and that AKBA can inhibit mitosis of glioblastoma cells by down-regulating the Aurora B/ TOP2A pathway." (PMID 29970196, 2018). "It has been shown that TBMS1 reduces cyclin B1, CDK1, and AKT phosphorylation levels and elevates the level of the cKd1 inhibitor p21, which inhibits DNA synthesis and induces G2/M phase block in glioblastoma cells by targeting the PI3K/AKT/p21 and p21/CDK1/cyclin B1 signaling cascades." (PMID 40061015, 2025). "Because BMAL1 knockdown in glioblastoma cells upregulates cyclin B1 expression, BMAL1 overexpression in cells might downregulate cyclin B1 expression." (PMID 32231148, 2020). "The mechanism by which CREB regulates glioblastoma tumor cell proliferation involves activities downstream from both the MAPK and PI3K pathways that then modulate the expression of three key cell cycle factors, cyclin B1, cyclin D1 and PCNA." (PMID 27926502, 2017). "In the present study, the decrease in MSI1 in glioblastoma cells led to cell growth retardation and a defect in non-apoptotic cell survival, accompanied by a cell-cycle abnormality, which resulted in an ectopic accumulation of Cyclin B1." (PMID 22428049, 2012). "However, Pin1 expression does not appear to significantly correlate with FOXM1, CENPF and Cyclin B1 expression in at least mammary, ovarian, renal and endometrial carcinomas and glioblastoma, suggesting the regulation of FOXM1 activity by Pin1 might be restricted to subsets of cancers." (PMID 26279295, 2016). "In good agreement with this hypothesis is a recent work showing that PI3K inhibition induces the arrest of glioblastoma cells in G2/M transition by down-regulating CDK1 and cdc25 expression without affecting the expression of cyclin B1." (PMID 23301080, 2013).
glioblastoma (continued). "In contrast, in human glioblastoma (GBM) cell lines CA did not down-regulate the PI3K/AKT pathway, whereas it induced proteasomal down-regulation of Retinoblastoma, Cyclin B1, SOX2 and GFAP and cell cycle arrest with only a minor induction of apoptosis." (PMID 29100552, 2017).
non-small cell lung carcinoma (33 papers, 2010 to 2025). A group of at least three distinct histological types of lung cancer, including non-small cell squamous cell carcinoma, adenocarcinoma, and large cell carcinoma. "Up-regulation of CCNB1 is consistently associated with high-expressions of GAPDH in non-small-cell lung cancer." (PMID 32635458, 2020). "In contrast, in other tumors including oesophageal, gastric, tongue, breast and non-small cell lung cancer, high level of Cyclin B1 was associated with aggressive tumor behavior." (PMID 25849598, 2015). "H Ma and colleagues reported that rs2069429 in CCNB1 was associated with non-small cell lung cancer survival." (PMID 24386390, 2013). "Four SNPs of CCNB1 (rs352626, rs350104, rs2069429, rs164390) were genotyped by H Ma and colleagues in 828 non-small cell lung cancer cases, and rs2069429 was found to be associated with NSCLC survival with a log-rank P<0.1 under recessive model." (PMID 24386390, 2013). "Additionally, researches in non-small cell lung cancer have shown that high levels of cyclin B1 (CCNB1) are associated with non-small cell lung cancer." (PMID 36287252, 2023). "Research has shown that several downstream targets of FOXM1, including survivin, cyclin B1, S-Phase Kinase-Associated Protein 2, and CDC25B, were significantly upregulated in non-small-cell lung cancer cells treated with gefitinib." (PMID 37242455, 2023). "This study showed that bortezomib had a similar effect on CDK1 and cyclin B1 in non-small cell lung carcinoma cell lines." (PMID 37834095, 2023). "Previously, miR-192-3p was reported to directly target cell cycle-promoted factor CCNB1 and suppress non-small cell lung cancer cell growth." (PMID 35109781, 2022). "Currently, Cyclin B1 overexpression has been found in a variety of human tumours, such as oesophageal cancer, non-small cell lung cancer, tongue cancer, and is related to tumour grade, differentiation, invasion, and metastasis, and prognosis." (PMID 35037540, 2022). "It has been reported that overexpression of CCNB1 was correlated with adverse pathological types and clinical outcomes, such as BC, colon adenocarcinoma, non-small cell lung cancer and esophageal squamous cell cancer." (PMID 34797837, 2021). "A previous study has also demonstrated that PS-341, a boronic acid dipeptide, induced G2/M phase arrest through a blockade of cyclin B1 degradation in human non-small cell lung cancer cells." (PMID 31739520, 2019). "The studies also suggested that the expression CCNB1 may be used as a predictive marker in patients with early stage non-small cell lung cancer." (PMID 36287252, 2023). "As a key mitotic cyclin, cyclin B1 induces the G2/M phase transition of the cell cycle, thus reducing the radiosensitivity in several types of cancers, such as nasopharyngeal carcinoma, squamous cell carcinoma, and non-small cell lung cancer." (PMID 34462422, 2021). "Cyclin B1 overexpression and/or mislocalization has been described in several primary cancers including breast, colon, gastric, prostate, thyroid carcinoma and non small-cell lung cancer (NSCLC)." (PMID 25625291, 2015). "One study found that docetaxel could suppress the expression of CCNB1 in non-small cell lung cancer NCI-H460 cells." (PMID 24386390, 2013). "In addition, elevated cyclin B1 has been reported in numerous cancers including gastric, colorectal, head and neck squamous cell carcinoma and non-small-cell lung cancer." (PMID 20846384, 2010). "Degradation of CCNB1 mediated by APC11 through UBA52 ubiquitination promotes cell cycle progression and proliferation of non-small cell lung cancer cells." (PMID 35008908, 2022). "Cyclin B1 (in the same family as CDK1) overexpression and/or mislocalisation has been described in several primary cancers, including thyroid carcinoma and colon, gastric, prostate, breast, and non small-cell lung cancers." (PMID 32093341, 2020).